SOX5 (SRY-box transcription factor 5)
Diseases named in the same sentence as SOX5 in open-access papers (continued):
Sharing a sentence is not in itself a finding about the gene and the disease.
tumor (continued). "Finally, the clinical implications were investigated by comparing the expression profiles of SOX5, SOX10 and MITF to clinically relevant parameters (overall survival and tumor stage), leading to a biomarker regression model (of SOX5, SOX10 and MITF)." (PMID 26927636, 2016). "Only for SOX5 expression, a clear tendency (p = 0.06) between the subgroups of primary tumor and metastases samples could be observed with a differential down-regulation of SOX5 in primary samples, when compared to metastatic samples." (PMID 26927636, 2016). "Finally, we demonstrate that SOX5 knockdown inhibits xenograft tumor growthin vivo." (PMID 35880568, 2022). "Therefore, lnc-sox5 may serve as a modulator of IDO1 in tumor cells and can be a potential therapeutic target for cancers." (PMID 32083005, 2020). "Moreover, SOX5 expression in adjacent non-tumor tissues was lower than in LAC tissues (P< 0.0001)." (PMID 29541384, 2018). "Interestingly, the effects of recombinant CCN2 peptide on U-CH1 cells were more pronounced under normoxia than hypoxia, promoting increased expression of CCN1, CCN2, CCN3 and CCN5, the notochord-associated markers SOX5, SOX6, T, CD24, and FOXA1 as well as increased tumour-sphere formation." (PMID 25541962, 2014). "SOX5, a transcription factor involved in epithelial-mesenchymal transition (EMT) and metastasis, has been shown to promote tumor progression in other cancers." (PMID 40697663, 2025). "The expression of SOX12 was higher in the tumor cell subgroup compared to normal subgroup, whereas other SOX transcripts, including SOX2, SOX5, SOX9, SOX11, and SOX15, had low expression in tumor clusters." (PMID 40593465, 2025). "By regulating the miR-497-5p/SOX5 axis, DHA not only inhibits tumor growth but also suppresses metastasis and induces apoptosis." (PMID 40697663, 2025). "In PCa, upregulation of TWIST1 through Sox5 increased the migration capacity and mesenchymal phenotype of cancer cells, initiated the EMT program, and promoted tumor lymph node metastasis." (PMID 36127329, 2022). "Functionally, the ectopic expression of SOX5 in HT29 and SW480 cells abrogated the tumor inhibitory behaviors induced by miR-194-5p unregulated." (PMID 33993197, 2021). "Knockdown of lnc-sox5 highly decreases the production of IDO1 and enhances the cytotoxicity of CD3+CD8+ CTLs at the tumor site." (PMID 31850199, 2019). "Silencing SOX5 in NCI-H1299 and 95D cells impeded cell proliferation and metastasis; increasing SOX5 in A549 and H1975 cells accelerated tumor progression." (PMID 29541384, 2018). "However, there is no exact explanation for the specific regulatory mechanism through which SOX5 affects tumor proliferation, invasion, migration and EMT during tumor progression." (PMID 38835366, 2024). "Interestingly, upregulated DEGs like SNCG (logFC 9.95), CPNE8 (logFC 7.18), GRIA3 (logFC 4.08), SOX5 (logFC 3.94) and CRISP3 (logFC 3.44) representing the highest log fold changes were involved in tumor cell metastasis and invasiveness." (PMID 37239828, 2023). "Overexpression of lncRNA SRY-box transcription factor 5 (lnc-sox5) in CRC cells leads to upregulation of IDO1 enzyme, which stimulates the differentiation of Tregs and eventually their infiltration into the tumor microenvironment." (PMID 34943820, 2021). "With the exception of clonal Pdgfra and Nav3 insertions in one tumor, transposon insertions in MAPK/PI3K pathway and neurodevelopmental genes (including Nf1, Pten, Pik3r1, Ptprj, Sox6, Sox5, and Tcf4) were subclonal in these tumors, implying these were late evolutionary events." (PMID 32727536, 2020). "Comparing tumor subgroups of NRAS mutated with NRAS wildtype, no significant expression differences were found except for SOX5 which was significantly overexpressed in NRAS mutated samples (p = 0.05)." (PMID 26927636, 2016).
tumor (continued). "Consistent with protein findings, quantitative RT-PCR demonstrated elevated SOX5 transcripts in tumors relative to matched controls (p < 0.001), while Western blotting confirmed SOX5 overexpression in tumor tissues compared to weak expression in non-tumorous tissues (p < 0.001)." (PMID 40697663, 2025). "TGF-β can induce SOX5 expression through Smad3 phosphorylation, and SOX5 can promote the expression of Twist1, resulting in overexpression of Twist1 and inducing EMT to promote tumor metastasis, while targeting SOX5 can effectively delay TGF-β signal-induced EMT." (PMID 38835366, 2024). "Additionally, the absence of lnc-sox5 did not affect the growth of tumor cells in immunodeficient mice, but significantly suppressed tumorigenesis in immunocompetent mice." (PMID 32083005, 2020). "According to our SOX5 expression scores, LAC tissue displays a positive correlation with paracancerous tissues (P<0.05), suggesting that SOX5 may perform similar biological functions in tumor tissue and tumor microenvironment." (PMID 29541384, 2018). "Also, both miRNAs act as tumor suppressors, inhibiting the expression of proteins involved in epithelial-mesenchyme transition (EMT) and tumorigenesis, especially the transcription factor Sox5 and Bcl2." (PMID 26681200, 2015). "Our data show that one of the identified murine genes, SOX5, actually promotes anchorage-independent growth of MDCK epithelial cells also when exogenously expressed in its human version, and further support a possible role for this gene in tumor onset and progression." (PMID 18510758, 2008).
cancer (38 papers, 2008 to 2026). A tumor composed of atypical neoplastic, often pleomorphic cells that invade other tissues. "SOX5, an important gene for embryonal development and chondrocyte differentiation, was associated to cancer development and metastasis, including HCC." (PMID 40489530, 2025). "This suggests that cancer-associated SOX5 can be used not only as a reliable diagnostic marker, but also as a potential therapeutic target." (PMID 38835366, 2024). "An RNA sequencing (RNA-seq) analysis comparing parental BRCA2-mutated cancer cells and olaparib-resistant cells identified SRY-box transcription factor 5 (SOX5) as one of the top candidate genes upregulated in olaparib-resistant cells compared to the corresponding parental cells." (PMID 40274769, 2025). "In addition, silencing SOX5 also causes cancer cell spindles to deform less and pseudopods to be shorter." (PMID 38835366, 2024). "Recent studies have found that SOX5 dysregulation are associated with cancer." (PMID 37531195, 2023). "Another interesting association with cancer can be observed in the SOX-5/miR-29a/SPARC circuit." (PMID 20731828, 2010). "However, aberrant SOX5 expression is associated with the progression of various cancers." (PMID 40274769, 2025). "Most genes were found related to the development of different cancer types and metastasis, such as MAGI-A23, EIF3E, and SOX5, while PDSD3 was associated to NAFLD." (PMID 40489530, 2025). "SRY-box transcription factor 5 (SOX5) plays a crucial role in development of various cancers but the role of SOX5 in PARP inhibitor resistance is poorly understood." (PMID 40274769, 2025). "SOX5, KANK1, and ZFHX3 are transcription factors implicated in specific cancer entities and regulate cell development, migration, and genomic stability." (PMID 40456839, 2025). "Meanwhile, many studies have confirmed that SOX5 plays an important role in the progression of various cancers." (PMID 38835366, 2024). "A series of studies have identified the important role of SOX5 in the development of resistance to chemotherapy, radiotherapy and targeted therapy in different types of cancer cells." (PMID 38835366, 2024). "Second, although Sox5 has been extensively studied in the field of cancer, current research is mainly limited to the cellular or rodent stage, and its expression level and chemical stability in body fluids have not been clearly verified." (PMID 38835366, 2024). "This chapter mainly introduces the expression of SOX5 in related cancers and its influence on cancer." (PMID 38835366, 2024). "(b) The mechanism by which SOX5 exerts its regulatory role in tumors, and the mechanism by which Sox5 affects the occurrence and progression of cancer." (PMID 38835366, 2024). "The expression pattern of SOX5 has been studied in a wide range of cancers and has been shown in the TCGA database to be significantly altered in a variety of cancers compared to normal tissues." (PMID 38835366, 2024). "Previous studies have found that SOX5, as an oncogenic gene, is involved in the development of various cancers." (PMID 38835366, 2024). "As an oncogene, the abnormal expression of SOX5 not only regulates the occurrence and development of various cancers, but also mediates the proliferation, metastasis, epithelial-mesenchymal transformation (EMT) and angiogenesis of cancer cells." (PMID 38835366, 2024). "Meanwhile, abnormal expression of SOX5 can also promote cancer proliferation, invasion and Epithelial to Mesenchymal Transition (EMT) by targeting different downstream genes such as Twist1, Snail and acidic secreted protein rich in cysteine." (PMID 38835366, 2024). "In this review, we summarize the role, mechanism and potential clinical significance of SOX5 in cancer pathology." (PMID 38835366, 2024). "More and more evidence shows that SOX5 is abnormally expressed as an oncogene in cancers of multiple human systems and involved in the occurrence and development of cancer." (PMID 38835366, 2024).
cancer (continued). "The TCGA database shows that the abnormal expression of SOX5 acts as an oncogene to promote the occurrence and development of tumors and the maintenance of cancer cell phenotypes." (PMID 38835366, 2024). "Down-regulating the expression of circDOCK1 can inhibit SOX5, thereby reducing cancer cell viability, inhibiting cell proliferation and inhibiting the cell migration potential of BC cells." (PMID 38835366, 2024). "Some studies believe that SOX5 is the target gene of multiple ncRNAs, and a variety of ncRNAs can target SOX5 to play a therapeutic role in cancer." (PMID 38835366, 2024). "The up-regulated expression of SOX5 can promote the occurrence and development of GC, and also promote the proliferation, distant metastasis and invasion of cancer cells." (PMID 38835366, 2024). "Proteins SOX5, SON, and OLR1 have been implicated in various aspects of cancer progression and metastasis." (PMID 38003292, 2023). "The remaining 26% either had anti-CCAR1 or anti-SOX5 in isolation, and only 1 of these patients (2% of the group with cancer) had them in combination with another antibody." (PMID 35040440, 2022). "To investigate the role of SOX5 in cancer progression, we first created a SOX5 overexpression plasmid (pcDNA-SOX5) based on the pcDNA-3.1 vector, then synthesized siRNAs against SOX5 (SOX5-siRNAs), and transfected them into T24 and J82 cells." (PMID 35880568, 2022). "SOX5 also regulates a variety of targets in cancers, including EZH2, twist 1, P2RY8, MITF, and others." (PMID 35880568, 2022). "We further analyzed SOX5 silencing in vivo using a zebrafish xenograft model, which has been used in cancer proliferation and metastasis analyses." (PMID 29541384, 2018). "Sex determining region Y-box protein 5 (SOX5) is known to stimulate the progression of various cancers." (PMID 29541384, 2018). "Sex determining region Y-box protein 5 (SOX5) expression is correlated with various cancers including prostate tumor, breast cancer, glioma, hepatocellular carcinoma and nasopharyngeal carcinoma." (PMID 29541384, 2018). "Because YAP/TAZ-TEAD transcriptional activity governs RAD51 expression in cancer cells, whether SOX5 inhibition regulates YAP and the HR repair genes, BRCA1 and RAD51, in olaparib-resistant cells was investigated." (PMID 40274769, 2025). "Our study also validated SOX5 as a promising therapeutic target by demonstrating that SOX5 inhibition in combination with PARP inhibitor shows synergistic anticancer activity in PARP inhibitor-resistant preclinical cancer models." (PMID 40274769, 2025). "As an oncogene, SOX5 is highly expressed in a variety of cancers." (PMID 38835366, 2024). "In addition, the expression pattern of SOX5 is closely related to cancer type, stage and adverse clinical outcome." (PMID 38835366, 2024). "Although SOX5 has not yet been reported to be specific and sensitive in which type of cancer than currently used diagnostic or prognostic markers, it is not difficult to find that SOX5 appears to be a promising diagnostic and prognostic factor." (PMID 38835366, 2024). "Mechanism of action of non-coding RNA targeting SOX5 in human cancer." (PMID 38835366, 2024). "However, knocking down SOX5 can reverse the colonization and survival ability of cancer cells in bone matrix." (PMID 38835366, 2024). "Further studies have shown that SOX5 can directly or indirectly down-regulate the expression of E-cadherin, up-regulate the protein expression of N-cadherin, Vimentin and fibronectin, thus promoting the occurrence of cancer EMT." (PMID 38835366, 2024). "So far, the function of SOX5 in different cancers is quite different." (PMID 37531195, 2023). "Some of the SOX genes have been associated with poor prognosis and cancer progression (SOX2, SOX5)." (PMID 37509311, 2023). "Sex determining region Y-box protein 5 (SOX5) plays important roles in a variety of human cancers." (PMID 35880568, 2022).
cancer (continued). "The up‐regulation of SOX2, SOX4, SOX5, SOX8, SOX9 and SOX18 are found to be associated with poor outcome in different cancer types; however, the up‐regulation of SOX11 and SOX30 is favourable for the prognosis in other cancer types." (PMID 32363730, 2020). "SOX5 knockdown reduced cancer cell proliferation three days post-inoculation." (PMID 29541384, 2018). "Similarly, AP-2rep, SOX5, and myogenin binding motifs were enriched in gene promoters hypermethylated in tumors, possibly implying role of these factors in cancer-specific aberrant methylation." (PMID 27690235, 2016). "Therefore, SOX5 is considered as a potential biomarker for cancer diagnosis and prognosis." (PMID 38835366, 2024). "Therefore, SOX5 may be a potential biomarker for cancer diagnosis and prognosis, as well as a potential target for cancer therapy." (PMID 38835366, 2024). "Abnormal expression of SOX5 in human cancer is closely related to the occurrence, development, migration, metastasis and prognosis of cancer, and SOX5 knockout can induce cancer cell cycle arrest and apoptosis, and inhibit the progression and migration of cancer." (PMID 38835366, 2024). "This suggests that Sox5 may serve as a biomarker for cancer diagnosis." (PMID 38835366, 2024). "However, very few studies focused on the correlation of SOX5 and cancer." (PMID 29541384, 2018). "In the cancer cells of the bladder, EGR1 promoted cell migration, invasion, and gemcitabine resistance by regulating SOX5." (PMID 39866235, 2025). "The most significantly upregulated DEGs such as SNCG, CPNE8, GRIA3, SOX5 and CRISP3 can be involved in metastasis and invasivity of cancer cells as well." (PMID 37239828, 2023). "For example, SOX5 and SOX6, members of the SOXD family, were frequently underexpressed concurrently in several cancer types." (PMID 25594027, 2014). "Of the 13 recurrently underexpressed SOX genes, SOX3, SOX5, SOX7 and SOX10 were exclusively underexpressed (i.e. they showed overexpression frequencies <20% in all cancer types)." (PMID 25594027, 2014). "SOX5 can promote cyclin D1/cyclin dependent kinase 4 (CDK4) complex, cyclin A and Rb phosphorylation, thereby reducing the percentage of G0/G1 phase cells and increasing the percentage of S phase cells, thereby promoting cancer cell proliferation." (PMID 38835366, 2024). "(b) While anti-CCAR1 antibodies in isolation were enriched in patients without cancer, anti-SOX5 autoantibodies in isolation did not have a similar association." (PMID 35040440, 2022). "In our models, Napabucasin treatment similarly reduced the stemness property of lung colonizing cancer cells, illustrated by a significant decrease in the expression of stemness genes, e.g. CK14, SOX5, SOX9, and HOXA4, and an increased expression of the differentiated cell marker, CK18." (PMID 31086186, 2019). "Similarly, levels of DNA methylation in RASSF2, SOX5, GALNT14 and miR-34b/c, four cancer-related genes, were strikingly higher in lesions located in the proximal colon (from the cecum to the descending colon) than in those in more distal subsites." (PMID 27145369, 2016). "The functional consequence of SOX5 amplification in human cancers has not been explored." (PMID 22355333, 2012). "Also, many targeted genes, such as ZEB1, SOX5, AKAP1, CHP1, CNBP, VEGFR, and MAGT1, play a vital function in the cell shape, movement, invasion, adhesion, and polarity formation, so as to involve in many kinds of diseases such as malignant tumors, wound healing, and so on." (PMID 32547593, 2020).
neurodevelopmental disorder (12 papers, 2017 to 2026). A behavioral and cognitive disorder with onset during the developmental period that involves impaired or aberrant development of intellectual, motor, or social functions. "Lamb–Shaffer syndrome (LAMSHF, OMIM 616803) is a neurodevelopmental disorder caused by mutations in the SRY-box transcription factor 5(SOX5) gene." (PMID 40500800, 2025). "Variable expressivity has been previously recognized between and within SOX5-mutated families and it is a very well-known phenomenon in a multitude of neurodevelopmental disorders." (PMID 29214085, 2017). "Whether the partial agonist properties of aripiprazole confer advantages in SOX5-related neurodevelopmental disorders remains unknown, but this case suggests that switching to an alternative agent with a different pharmacodynamic profile is a reasonable strategy when paradoxical reactions occur." (PMID 41531626, 2025). "These include 10 that we classified as high interest VUS (ACMG total score = 0.60–0.75), such as SOX5 (delayed speech and language development) and BRSK2 (neurodevelopmental disorders)." (PMID 40325133, 2025).
infection (3 papers, 2015 to 2025). The state of being infected such as from the introduction of a foreign agent such as serum, vaccine, antigenic substance or organism. "SusceptibleMac specifically upregulated pro-viral factors LEF1 and SOX5, while RepairMac maintained stable transcription factor networks despite infection." (PMID 40723441, 2025). "Toward this we knocked down some important transcriptional regulators such as CREB, c-JUN, and SOX-5 in macrophages prior to infection with MTB." (PMID 26697414, 2015).
psychiatric disorder (2 papers, 2022). A disorder characterized by behavioral and/or psychological abnormalities, often accompanied by physical symptoms. "SOX5 has been identified as a gene with a high pleiotropic effect on a broad spectrum of psychiatric disorders and has been associated especially with ASD, BIP, MD, and SCZ, and to a lesser degree also with OCD, TS, ADHD, and AN." (PMID 36379924, 2022).
skeletal dysplasia (2 papers, 2009 to 2022). Any Mendelian diseases that affects growth and development of the skeleton. "Although mice deficient in Sox5 or Sox6 alone survive with mild skeletal dysplasia, the formation of cartilage in Sox5/Sox6 double-knockout mice is harshly compromised." (PMID 36339269, 2022). "Mouse SOX5/SOX6 double knockouts die in utero with severe skeletal dysplasia, demonstrating that these two genes have critical, redundant roles during development." (PMID 19521496, 2009).
CNS tumors (1 paper, 2022). "SOX5 and SOX9, as members of the SOX family, are implicated in the development and maintenance of CNS tumors." (PMID 36231068, 2022).